MEG3 (maternally expressed 3)
Diseases named in the same sentence as MEG3 in open-access papers (continued):
Sharing a sentence is not in itself a finding about the gene and the disease.
cancer (continued). "MEG3 is involved in modulating drug resistance to chemotherapy in multiple types of human cancers." (PMID 34055623, 2021). "Additionally, four lncRNAs were described as downregulated (e.g., LET, GCASPC, and MEG3), also acting as agents whose low expression promotes malignant tumor characteristics in these patients, worsening the overall survival (OS) in these patients." (PMID 34575316, 2021). "MEG3 is downregulated in many cancers, such as breast, cervical, gastric, lung, and EOC." (PMID 34680193, 2021). "In addition, the rescue experiment showed that MEG3 overexpression attenuated the enhancing effects of POU3F3 overexpression on cancer cell proliferation (p < 0.05)." (PMID 35201451, 2021). "Thus, restoring the MEG3 expression can inhibit the cancer cell’s proliferation and prompt their apoptosis." (PMID 34885213, 2021). "Overexpressed MEG3 significantly reduces cancer proliferation and metastasis and can induce apoptosis of EC cells either by regulating the Notch1 signaling pathway or by downregulating the expression of PI3K protein and its downstream genes, including BCL-XL, VEGF-A, P70S6K, and Mtor." (PMID 34885213, 2021). "MEG3 is a second lncRNA that is often downregulated in cancer." (PMID 34065345, 2021). "The role of MEG3 in various types of stem cells and cancer stem cells is discussed." (PMID 34069546, 2021). "Overexpression of the 14q32 cluster miRNAs has been associated with the CCCTC-binding factor (CTCF)-mediated regulation of the maternally expressed gene 3 differentially methylated region (MEG3-DMR) or global genomic hypomethylation of 14q32 locus as reported in various cancers, including CLL." (PMID 34750354, 2021). "The correlation of LncRNA MEG3 with miR-543 in carcinoma tissues was analyzed." (PMID 34399782, 2021). "LncRNA MEG3 and miR-543 in carcinoma tissues and adjacent tissues in the RG were detected." (PMID 34399782, 2021). "Long non-coding RNA maternally expressed gene 3 (MEG3) serves a regulatory role in the carcinogenesis and progression of several types of cancer; however, its role in CRC remains largely unknown." (PMID 32219064, 2020). "To support and expand these findings, we also proved a close relationship between MEG3 expression levels and modulation of cancer cell related processes in preclinical models of HGSOC, finally providing a new paradigm for developing therapeutic strategies for cancer treatment." (PMID 32295169, 2020). "Summarizing these results, we believe that MEG3 played a role in cancer development while ZEB1-AS1 could act in both carcinogenesis and cancer development." (PMID 33101392, 2020). "Indeed, circulating HOTAIR, MALAT1, and MEG3 transcripts were found significantly higher in cancer patients compared to healthy subjects suggesting their potential as diagnostic biomarkers." (PMID 32154165, 2020). "Although MEG3 was reported to be involved in tumorigenesis and development of various cancers, the function and molecular mechanism of MEG3 in NB remains unclear." (PMID 33061817, 2020). "MEG3 is downregulated in a variety of malignant tumors and acts as a tumor suppressor." (PMID 33519750, 2020). "In previous studies, MEG3 promoted or inhibited autophagy in various cancers." (PMID 33061817, 2020). "Lower expression of MEG3 in HNSCC has been verified in cancer tissues and cell lines." (PMID 32277605, 2020). "Restoring the expression of MEG3 could suppress cancer initiation, progression, metastasis and chemoresistance." (PMID 33363153, 2020). "It has been reported that MEG3 plays a role in suppressing cancer by upregulating p5337." (PMID 33299646, 2020). "Additionally, MEG3 can act in multiple cancer types as a ‘sponge’ of various miRNAs, thereby inhibiting the promotion of cancer phenotypes." (PMID 33066171, 2020).
cancer (continued). "lncRNA MEG3 is widely recognized as a tumor suppressor gene in several types of human cancers." (PMID 33029125, 2020). "MEG3, a kind of long noncoding RNA (lncRNA), participates in cell proliferation in cancer tissues." (PMID 31411001, 2019). "In addition to cancer cells, MEG3 is also expressed in other cells such as immune cells and fibroblasts, and affects their gene expression patterns." (PMID 31729423, 2019). "MEG3 has been also found in exosomes from cervicovaginal lavage of cancer patients." (PMID 30395586, 2018). "MEG3 expression is prevalent in human normal tissues, while it becomes diminished in most human tumors, and overexpression of MEG3 inhibits the growth of human cancer cells." (PMID 30116729, 2018). "LncRNAs can regulate cancer cell migration by targeting Rho/ROCK signaling and include metastasis-associated lung adenocarcinoma transcript 1 (MALAT1), actin filament associated protein 1 antisense RNA1 (AFAP1-AS1), and maternally expressed 3 (MEG3)." (PMID 29618386, 2018). "In our meta-analysis, we assessed the prognostic role of MEG3 in cancers." (PMID 28157702, 2017). "In conclusion, this meta-analysis indicated that MEG3 might serve as a potential novel biomarker for indicating the clinical outcomes in human cancers." (PMID 28157702, 2017). "Moreover, we also selected five representative disease lncRNAs (HOTAIR, MALAT1, H19, MEG3 and TUG1) that play key roles as oncogenic molecules associated with various cancers to investigate their occurrences at the top 5%-20% of the candidate lists." (PMID 28076842, 2017). "It is reported that apoptosis induced by MEG3 has also been observed in cancer cells." (PMID 29348851, 2017). "Together, lncRNA MEG3 may not only act as a potential therapeutic target, but also as a novel prognostic biomarker in cancer." (PMID 28157702, 2017). "Recent data suggest a process of loss of imprinting (LOI) in this region, which is involved in cancer development, and a correlation between methylation patterns in the MEG3 promoter and expression of several miRNAs in the 14q32 ncRNA cluster has been suggested." (PMID 28506242, 2017). "Restoring the expression of MEG3 impedes cancer cell proliferation in vitro." (PMID 29069869, 2017). "Cancer cells with MEG3 overexpression grew significantly slower than the control cells." (PMID 29348851, 2017). "Lost or decreased expression of MEG3 is common in human cancers." (PMID 29069869, 2017). "MEG3 has a strong ability to inhibit proliferation of several carcinoma cell lines and NFPA." (PMID 29069869, 2017). "Therefore, elucidating the mechanisms by which MEG3 expression can be restored will give insight into potential new cancer therapeutics." (PMID 27832204, 2016). "Furthermore, the treatment of human cancer cell lines with a methylation inhibitor results in MEG3 expression." (PMID 26637808, 2016). "Decrease of MEG3 expression has been observed in several types of cancer." (PMID 25387074, 2014). "Recently, the downregulation of lncRNA MEG3 has been observed in various human cancers." (PMID 24098911, 2013).
cancer (continued). "These advantages suggest that MEG3 could revolutionize cancer diagnostics." (PMID 40242248, 2025). "Notably, MEG3, MIAT, Malat1, SNHG20, SNHG12, Ftx, Pvt1, Mir9-3hg expression in cancer immune cells was associated with an immunosuppressive phenotype, while H19, SNHG6, Trp53cor1, MiR17hg and MiR142hg were linked to a pro-inflammatory phenotype in cancer." (PMID 40527978, 2025). "Likewise, up-regulation of lncRNA HOTAIR and MALAT1, down-regulation of lncRNA Meg3 and dual function of lnRNA H19 were seen in different cancer types, including lung cancer, ovarian cancer, prostate cancer, breast cancer, colorectal cancer, gastric cancer, and liver cancer." (PMID 37568568, 2023). "However, MEG3 expression is typically suppressed in a variety of cancer tissues." (PMID 34956908, 2021). "Therefore, POU3F3 could also interact with other downstream pathways to reverse the enhancing effects of MEG3 inhibition on cancer cell migration and invasion." (PMID 35201451, 2021). "However, dysregulation of MEG3 expression may lead to the development and proliferation of cancer, suggesting a potential biomarker and therapeutic target in human cancers." (PMID 34885213, 2021). "Moreover, elevated expression of MEG3 can inhibit cell invasion, proliferation, and apoptosis induction, indicating that MEG3 might be a novel therapeutic target for cancers." (PMID 34527584, 2021). "Hence, the incremental chemosensitivity of BC cells might, to some extent, result from the inhibition of MEG3 on EMT process of cancer cells." (PMID 32618397, 2020). "The role and source of circulating MEG3 in cancer patients is unknown." (PMID 31231466, 2019). "MEG3 may therefore play an important role in the development of cancers." (PMID 31654067, 2019). "Among the 19 TSLNRs in this study, only eight (EPB41L4A-AS2, MEG3, LINC-PINT, FTX, HCG11, HAND2-AS1, SNHG5 and TPT1-AS1) have been reported previously to be associated with malignancy, and the potential functions of the other 11 lncRNAs in human cancer remain a mystery." (PMID 30764831, 2019). "Thus, our exploration of Meg3 may also suggest new avenues for treating other diseases, such as cancers, as well as in elucidating the reprogramming mechanism of iPSCs." (PMID 30311912, 2018). "In addition, the level of MEG3 showed good correlation with cancer clinicopathological grade." (PMID 29069869, 2017). "From these results, lncRNA MEG3 could be as biomarker for the prognosis of cancers." (PMID 28157702, 2017). "•MMP-2 and MMP-9 Regulation: Knockdown of MEG3 increased MMP-2 and MMP-9 expression, promoting cancer cell invasion." (PMID 41480643, 2026). "Compared to primary cancer samples, genes such as GLYATL2, EDIL3, MEG3, FABP4, ASCL1, GRP, and WDFY4 were highly upregulated in CRPC, with statistically significant differences underscoring their potential roles in driving the castration-resistant phenotype." (PMID 40165961, 2025). "Lower expression of MEG3 has been reported to have major impacts on cell proliferation, apoptosis, and EMT in cancer development." (PMID 40548301, 2025). "The role of MEG3 in RCC has been investigated in many studies, shedding light on its impact on cancer progression and potential therapeutic implications." (PMID 40242248, 2025). "Mechanistically, the identified axis of MEG3 was miR-208/SOX4, which was also proven to play a role in cancer stem cell functionality." (PMID 41463281, 2025). "As outlined in the manuscript, several lncRNAs, such as HOTAIR, MEG3, and MALAT1, have shown strong correlations with cancer progression, metastasis, and resistance to therapies." (PMID 39512820, 2024). "Another study found that MEG3, GAS5, and several miRNAs influence NK cell killing effectiveness in various cancer types." (PMID 39257589, 2024).
cancer (continued). "For instance, maternally expressed 3 (MEG3) exhibits show differential expression in HD, AD, and ALS and a few malignant tumors." (PMID 39691424, 2024). "Given the emerging applications of MEG3 and linc-ROR in cancer biology, further access to their co-expression patterns is needed to better understand their regulatory roles and synergistic effects in CRC cells." (PMID 39108882, 2024). "The colon-specific activity of the CEA promoter was assessed by evaluating the expression of MEG3 and linc-ROR in HCT116, SW480, and HeLa cancer cells." (PMID 39108882, 2024). "In the same context, relevant reports have shown that lncRNAs H19, MEG3, CPS1-IT1, and lnc010561 also display biological interactions with melatonin in cancer which are related to apoptosis, pyroptosis, and metastasis." (PMID 36332600, 2023). "When the demethylation reagent 5-AzadC is applied, the hypermethylation regulation of MEG3 by DNMT1 is significantly inhibited, and uninhibited MEG3 exerts its inhibitory effect on cancer through the inhibition of Notch1 signaling pathway." (PMID 37901333, 2023). "Whereas in hepatocellular carcinoma, MEG3 was found to contribute to the EMT phenotype and therefore increased the migration and invasion of the cancer cells." (PMID 37525401, 2023). "They reported also the expression level of MEG3 was significantly decreased in OSCC and overexpression of MEG3 inhibited the proliferation and metastasis of cancer cells and promoted apoptosis." (PMID 35898889, 2022). "For cancer samples, the expression level was higher than in normal samples for DAPK1, MLH1 and MALAT1, and lower for MEG3, TIMP3 and SOX1." (PMID 35682732, 2022). "Several lncRNAs involved in the local repression of imprinted loci also show significant deregulation in cancer, including KCNQ1OT1, H19, and maternally expressed gene 3 (MEG3), which are frequently overexpressed in a wide range of cancer types." (PMID 34668345, 2022). "MEG3 can repress CSC self-renewal ability and decrease cancer stemness phenotype in oral CSCs by blocking miR-421." (PMID 36551518, 2022). "For cancer samples, DAPK1, MLH1 and MALAT1 had higher expression, and MEG3, TIMP3 and SOX1 had lower expression when compared to normal samples." (PMID 35682732, 2022). "By these scRNA-seq transcript data, we identified four signatured cancer cell clusters, one of which was mostly derived from metastatic PDAC tumors and marked by MEG3 transcripts." (PMID 34055623, 2021). "A multitude of lncRNAs, such as HOTAIR, H19, MALAT1, MEG3, LET and PVT1, are correlated with cancer development." (PMID 34552067, 2021). "Hence, MEG3 could be a suitable biomarker candidate for clinical cancer management." (PMID 34527584, 2021). "More interestingly, most of the signature genes in Cluster 1 were same to those of metastatic cancer cells, including REG1B, MEG3 and CPA1, this was possibly because of the major cell contribution of this cluster from metastatic PDAC." (PMID 34055623, 2021). "Enrichment analysis indicated that the most target genes of MEG3 were enriched in the “MAPK signaling pathway”, “proteoglycans in cancer”, and “cAMP signaling pathway”, in which the gene-ratio of the “MAPK signaling pathway” reached up to 0.059." (PMID 34031265, 2021).
cancer (continued). "MEG3 expression can be negatively regulated by another lncRNA: AGAP2-AS1, which is upregulated in OC and participates in cancer cell proliferation." (PMID 34680193, 2021). "Among them, MEG3 and MIR7-3HG are related to cancer pathways, while these two and EPB41L4A-AS1 all regulate the JAK/STAT signalling pathway." (PMID 33499813, 2021). "For example, MEG3 has been demonstrated to be differently expressed in AD, ALS, HD and some malignant tumors." (PMID 34527672, 2021). "This subcluster, specifically marked by the expression of MEG3, showed significantly increased signatures of EMT and displayed a leading potential in cancer cell metastasis." (PMID 34055623, 2021). "Among the cluster, previous researches have shown MEG3 and MEG8 significantly contribute to epigenetic EMT in the malignant progression of cancer." (PMID 34906173, 2021). "Here, we aimed to explore the role of MEG3 as a prognostic biomarker in a homogenous series of advanced HGSOC patients, as well as to investigate its function in cancer development." (PMID 32295169, 2020). "At present, other therapeutic agents have been exploited against MEG3, GAS5, and HOTAIR, but their effect in HPV-driven cancers still remain to be defined." (PMID 32429207, 2020). "As a result, we found that MEG3 presented similar expression levels in both contexts (p = 0.66), while ZEB1-AS1 showed a significantly higher expression in cancer samples (p = 3.983 × 10–09)." (PMID 33101392, 2020). "Conversely, demethylation of MEG3 promoter by using 5-aza-2-deoxycytidine upregulated MEG3 expression and reduced proliferation of HPV-positive HeLa and CaSki cells, indicating the potential use of epigenetic drugs in HPV-driven cancers." (PMID 32429207, 2020). "MEG3 or ZEB1-AS1 regulate mRNAs by synergistic interactions with miRNAs, and further participate in cancer biological processes." (PMID 33101392, 2020). "In this study, we addressed the clinical relevance of MEG3 in HGSOC and its implication in cancer biology." (PMID 32295169, 2020). "In this mini-review, we summarized the recent understanding of the molecular mechanisms of PKM2-associated LncRNAs, including MAFG-AS1, HULC, FEZF1-AS1, LincRNA-p21, MEG3, HOXB-AS3, TP53TG1 and Linc-ROR in cancer metabolism." (PMID 31654067, 2019). "The validation results were highly in great agreement with those in microarray, and the expression tendency of HOTAIR, TINCR, LINC00511, LINC00520, MEG3, and ZNF667-AS1 was also consistent with literature reports in other carcinomas." (PMID 31196171, 2019). "Increasing lncRNAs have been reported to regulate cancer pathways and participate in cancer development, such as the well-characterized MALAT1, H19, HOTAIR and MEG3." (PMID 29849506, 2018). "Previous studies have shown a suppression of MEG3 gene in various tumors and a downregulation of MEG8 gene, which is essential for stem cell growth and proliferation, thus resulting into a cancer cell." (PMID 30647841, 2018). "To understand the mechanisms by which cancer-related lncRNAs are deregulated by KSHV, and their contribution to pathogenesis, we chose to initially study UCA1, ANRIL and MEG3." (PMID 28715488, 2017). "The growth of several cancer cell lines (such as HeLa and MCF7) is inhibited by MEG3 overexpression." (PMID 28637507, 2017). "MEG3 has also been found to suppress cell proliferation and promote apoptosis through the VEGF pathway, Wnt/β-catenin pathway and TGF-β pathway in some cancers." (PMID 29069869, 2017). "In particular, known disease lncRNAs, MEG3 and MALAT1, frequently occurred in 9 and 10 cancer types in the top 10% of candidate disease lncRNA lists, respectively." (PMID 29383105, 2017). "Thus, MEG3 could be considered as a potential prognostic factor for various cancers." (PMID 28157702, 2017). "Some well-known cancer-associated lncRNAs, such as H19, XIST, HOTAIR, MALAT1, MEG3, HNF1A-AS1 and PVT1, have indicated oncogenic and/or tumor suppressive roles like protein-coding genes in various cancers." (PMID 27074572, 2016).